BDNF (brain derived neurotrophic factor)
Diseases named in the same sentence as BDNF in open-access papers (continued):
Sharing a sentence is not in itself a finding about the gene and the disease.
Obesity (continued). "In the mature central nervous system, BDNF is expressed in various hypothalamic nuclei associated with eating behavior and obesity (Kernie, Liebl & Parada, 2000)." (PMID 25825681, 2015). "These genes include extensively replicated genes such as BDNF, which is not only shown to be associated with adult obesity but also with childhood obesity." (PMID 25806089, 2015). "For instance, complete post-natal inactivation of BDNF in mice was associated with hyperphagic obesity, whereas pre-natal inactivation of the same gene was lethal." (PMID 25825681, 2015). "Heterozygous BDNF deficiency in mice results in hyperphagia and obesity, while peripheral injection of the factor is anorexigenic." (PMID 25153796, 2014). "For instance, obesity is associated with altered levels of circulating biomarkers, including leptin, ghrelin, and brain derived neurotrophic factor (BDNF), among others." (PMID 25984353, 2014). "On the other hand, MC4R and BDNF mutations are known to cause monogenic obesity, and common variation in these genes has also been previously associated with severe obesity." (PMID 23950976, 2013). "It is possible that BDNF increases in obesity to compensate for its associated pathophysiologic conditions because of its potential role in improving energy metabolism." (PMID 25089225, 2013). "Blood BDNF levels of normal weight persons have been compared with those of obese persons, and the results of our study are consistent with the documented positive association between BDNF and obesity." (PMID 25089225, 2013). "In conclusion, we demonstrated that a common variation of BDNF is associated with T2DM independently of obesity in the Chinese Han population." (PMID 23431394, 2013). "Second, our analyses revealed positive associations between BDNF and obesity, suggesting that BDNF is a candidate molecule involved in the pathophysiology of weight disorders among PLWH." (PMID 25089225, 2013). "It is also involved in the control of appetite and body weight, with mutations in the genes for BDNF and its receptor, TrkB, resulting in remarkable hyperphagia and severe obesity in humans and mice." (PMID 23519010, 2013). "Subjects with BDNF levels above 8000 pg/ml had an increased risk of obesity (OR 1.4 95% CI 1.1–1.8, p=0.001)." (PMID 25089225, 2013). "To further characterize the risk of BDNF status on obesity, we dichotomized BDNF levels above and below 8,000 and estimated the likelihood of being overweight, obese, or abdominally obese using logistic regression models." (PMID 25089225, 2013). "A meta-analysis of associations between BMI and approximately 2.4 million SNPs in 27,715 East Asian subjects with replication studies in 37,691 and 17,642 additional East Asian subjects confirmed that loci at MC4R and BDNF were associated with obesity." (PMID 23431394, 2013). "In summary, our study demonstrated a significant association between BDNF levels and obesity traits in a sex-specific manner." (PMID 25089225, 2013). "Careful mapping of the deletion regions in 33 patients with the WAGR syndrome has identified haploinsufficiency of BDNF as the cause of the accompanied obesity disorder." (PMID 23519010, 2013). "The direct role of BDNF in metabolism is supported by studies on BDNF-deficient mice, which developed diabetes and obesity in early adulthood." (PMID 23968401, 2013). "Consistently, a positive association between peripheral BDNF and body weight has been found in women with obesity." (PMID 22768299, 2012). "Studies in animals have shown that mice with only one functional BDNF allele exhibited a tendency toward obesity." (PMID 22768299, 2012). "Potassium channel, calcium activated, large conductance, subfamily M, alpha member (KCNMA1) rs2116830*G and BDNF rs988712*G were associated with obesity in five of six investigated case-control cohorts." (PMID 21708048, 2011).
Obesity (continued). "BDNF is involved in neuronal survivability, differentiation and formation of memory and has also been associated to obesity in recent GWA-studies." (PMID 22087873, 2011). "In mice, genetic models deficient of BDNF signaling exhibit hyperphagia and obesity in addition to suppressing hippopcampal neurogenesis." (PMID 21837282, 2011). "We have identified KCNMA1 as a new susceptibility locus for obesity, and confirmed the association of the BDNF locus at the genome-wide significant level." (PMID 21708048, 2011). "Particularly surprising from our analyses was the finding that the obesity risk allele of BDNF (rs4923461) was borderline associated with a reduced risk of type 2 diabetes when adjusted for BMI." (PMID 21912638, 2011). "While homozygosity for the BDNF gene deletion is lethal, BDNF haploinsufficiency is associated with hyperphagia and obesity and elevated endocrine appetite/dietary factors." (PMID 20404913, 2010). "Studies using animal models have shown that conditions linked to metabolic and cardiovascular dysfunction, e.g. obesity, diabetes, heart disease, can be modified by manipulation of BDNF in the brain and in the peripheral circulation." (PMID 20404913, 2010). "A contiguous syndrome, the WAGRO syndrome (OMIM 612469), includes the features of WAGR with obesity and is caused by a similar deletion that includes the Brain-derived neurotrophic factor, BDNF gene as well." (PMID 19862335, 2009). "The loss-of-function mutations of BDNF or trkB loci in mice led to a syndrome of hyperphagia and obesity." (PMID 18382675, 2008). "The default state of the TrkB system in the whole body appears to be anorexigenic as indicated by the fact that rodents or humans carrying a loss of function allele of BDNF or TrkB locus exhibited early onset obesity and hyperphagia." (PMID 18382675, 2008). "In humans, genetic disruption of the neurotrophin receptor TrkB and in its ligand BDNF cause severe hyperphagia and obesity, developmental delay, impaired short-term memory and unusually hyperactive behavior." (PMID 17448988, 2007). "Gender disparities in the association of BDNF rs6265 genotype with obesity have been observed." (PMID 40697550, 2025). "Finally, polymorphisms in genes such as DRD2 and BDNF have been identified as shared factors associated with both dyslexia and obesity." (PMID 40740817, 2025). "BDNF polymorphisms might influence serum concentration and plasma BDNF levels further correlate with obesity and the BDNF Val66Met SNP." (PMID 40697550, 2025). "Single nucleotide polymorphisms such as FTO rs9939609, MC4R rs17782313, and BDNF rs6265, have been consistently associated with elevated body weight and an increased risk of obesity across diverse populations through their roles in appetite regulation, satiety, and energy balance." (PMID 40423790, 2025). "The BDNF gene has been associated with obesity in genome-wide association studies." (PMID 40724847, 2025). "Finally, mice and humans heterozygous for mutations that inactivate BDNF or TrkB develop hyperphagic obesity, suggesting a role for BDNF in inhibiting hunger." (PMID 40171198, 2025). "Second, the debate on the association between obesity and BDNF levels may be related to genetic polymorphisms in BDNF in different populations." (PMID 40697550, 2025). "Therefore, serum BDNF seemed to be a putative target for plant extracts and implicated in the amelioration of metabolic deregulations related to obesity." (PMID 40255947, 2024). "Additionally, hypothalamic BDNF and TrkB expression is significantly downregulated in Prader–Willi syndrome patients, who are susceptible to hyperphagic obesity." (PMID 38672441, 2024). "Several recent studies indicate that BDNF polymorphisms are associated with obesity." (PMID 39194496, 2024). "Since consumption of an HFD is associated with reduced levels of BDNF, this may be a mechanism through which exercise can improve cognitive dysfunction observed in obesity." (PMID 39871877, 2024).
Obesity (continued). "Adipose tissue-derived BDNF also plays a crucial role in metabolism by regulating local processes in white adipose tissue, such as sympathetic innervation, mitochondrial function, and susceptibility to obesity-related challenges." (PMID 39203753, 2024). "In a study involving human newborn infants at risk for perinatal ID due to maternal anemia, diabetes, or obesity, cord blood exosomal contactin-2 and brain-derived neurotrophic factor (BDNF), both of which are important for brain development, correlated with cord blood SF." (PMID 38613125, 2024). "Similarly, BDNF deficiency in the liver impairs metabolic regulation, resulting in hepatic steatosis and obesity." (PMID 39655343, 2024). "This study examined, in youth with obesity, whether carriers of the BDNF Val66met polymorphism Met‐alleles (A/A or G/A) differed from noncarriers (G/G) on HRQoL." (PMID 38997217, 2024). "Moreover, in humans, the BDNF Val66Met polymorphism has also been associated with eating disorders and obesity." (PMID 39194496, 2024). "The BDNF-deficient mice develop mature-onset obesity, primarily due to overeating." (PMID 39194496, 2024). "Similarly, individuals with Rett syndrome, characterized by a deficiency in central BDNF, are reported to have a higher risk of obesity." (PMID 39655343, 2024). "Also, mutations in the BDNF gene and its receptor TrkB in mice and humans caused an increase in food consumption, and contributed to the onset of severe obesity." (PMID 38785805, 2024). "Additionally, BDNF rs6265 and rs925946 have been incorporated into GRS association studies with obesity in European origin, and BDNF rs6265 among the Pakistani population." (PMID 38732542, 2024). "The brain derived‐neurotrophic factor (BDNF) Val66Met polymorphism causes functional changes in BDNF, and is associated with obesity and some psychiatric disorders, but its relationship to health‐related quality of life (HRQoL) remains unknown." (PMID 38997217, 2024). "Indeed, circulating BDNF has been implicated in the pathophysiology of several neurological disorders, including cognitive decline associated with obesity." (PMID 38785805, 2024). "The strengths of our study included its novelty, a high risk sample of youth with obesity who exhibit a greater incidence of BDNF‐related complications such as neurocognitive deficits, metabolic dysregulation, and reduced HRQoL compared to peers without obesity." (PMID 38997217, 2024). "In addition, genome-wide association studies have suggested a role for BDNF in the development of obesity." (PMID 39443799, 2024). "Furthermore, the information on these two BDNF polymorphisms with regard to obesity, cardiometabolic parameters, and plasma BDNF concentrations remains scarce, especially among Thai children." (PMID 37007871, 2023). "The aim of this study was to examine fasting serum BDFN concentrations in adolescents with MetS, either with normal-body mass index (BMI) or with obesity and to explore potential associations of circulating BDNF concentrations with sex, anthropometric, metabolic, and endocrine parameters." (PMID 37548699, 2023). "Regarding the BDNF polymorphisms, there is insufficient data to determine whether the BDNF C270T polymorphism is linked to obesity, BDNF level, and cardiometabolic profile, especially in children." (PMID 37007871, 2023). "Our results suggest that glucose homeostasis and obesity-related parameters in carriers of some common variants of BDNF gene, especially in the GG (rs10835211) genotype carriers, may differ dependently on daily energy, dietary macronutrients and fiber intake." (PMID 37085692, 2023). "We hypothesized that there would be a higher frequency of the BDNF G196A polymorphism among Thai children with low plasma BDNF levels or with obesity, but the present study rejects this hypothesis." (PMID 37007871, 2023). "Finally, more clinical studies are needed to explain the relationship and underlying mechanisms between obesity and BDNF." (PMID 37120612, 2023).
Obesity (continued). "Research has linked the dysregulation of the BDNF gene to, both, obesity and diseases of the CNS." (PMID 37548699, 2023). "As a myokine, muscle-generated BDNF is implicated in maintaining muscle’s mitochondrial quality, and its expression during obesity might involve metabolism impairments." (PMID 37408184, 2023). "In people with T2DM, lower levels of BDNF were associated with obesity and diabetes complications." (PMID 36970903, 2023). "Our study suggests that there may exist some associations between BDNF gene and diet that may have a significant impact on body weight, obesity-related parameters, glucose metabolism, and lipid profile." (PMID 37085692, 2023). "Nevertheless, contrasting results in the association of the BDNF C270T polymorphism with any obesity-related traits, cardiometabolic profiles and BDNF levels could be explained by the different ethnic backgrounds and behaviors of the study participants." (PMID 37007871, 2023). "BDNF depletion in the hypothalamus, BDNF haploinsufficiency, and mutation of its receptors have been reported to be related to increased dietary intake, weight gain, hence obesity." (PMID 37436597, 2023). "In female adolescents, obesity may activate the compensatory mechanism of BDNF upregulation, causing higher concentrations, whereas chronic obesity can lead to inadequate BDNF production, comparably evidenced in other disorders with BDNF upregulation." (PMID 37548699, 2023). "Mutations that reduce BDNF and TrkB expression are associated with obesity in humans and mice." (PMID 35338053, 2022). "Very recently, BDNF p.Thr2Ile and p.Arg209Gln missense variants were found associated with severe obesity developed during childhood in a 35-year-old and a 46-year-old female patient respectively, thus suggesting a potential obesogenic role of this gene variant." (PMID 36452324, 2022). "Some animal model studies found that a deleted BDNF gene in mice causes hyperphagic obesity." (PMID 36676721, 2022). "Hence, we suggest that the BDNF polymorphism rs6265 can be used as an early biomarker for the identification of intellectual disability, predisposition to obesity, and increased risk for cardiovascular events." (PMID 36742047, 2022). "However, the association between circulating levels of BDNF and obesity remains undefined and is based on the assumption that circulating BDNF mirrors concentrations in the brain." (PMID 35271679, 2022). "Finally, a functional polymorphism of the BDNF gene (BDNF Val66Met), which impedes the correct secretion and signaling of BDNF, was correlated with obesity predisposition in children and adolescents." (PMID 35242012, 2022). "Future investigations with many subjects are required to understand the mechanism by which BDNF affects obesity, the role of gene mutation in BDNF function, and whether administrating BDNF protein constitutes a new approach to treating obesity." (PMID 36676721, 2022). "In summary, the data obtained from this study support our hypothesis that low serum levels of BDNF protein are associated with high BMI and obesity in Saudi adults." (PMID 36676721, 2022). "In addition, dominant forms of non-syndromic monogenic obesity in humans have been associated with mutations in BDNF gene, encoding for the protein involved in proliferation and survival of hypothalamic neurons." (PMID 36452324, 2022). "Indeed, the role of BDNF in the mesolimbic pathway has been investigated in both pain syndrome and obesity and structural changes have been associated with specific amendments in reward and stress circuit targets related to motivation control." (PMID 34591410, 2021). "We used data from the Guangzhou Biobank Cohort Study (GBCS) to analyze the associations of the BDNF SNPs with general obesity and central obesity separately in Chinese by smoking status to test the hypotheses." (PMID 34525971, 2021).
Obesity (continued). "Furthermore, the T allele of rs925946 polymorphism (BDNF gene) was also associated with increased risk of obesity in early-onset psoriasis (OR: 2.26 (1.24; 4.14), p = 0.008)." (PMID 34685457, 2021). "Haploinsufficiency for BDNF or its receptor TrkB is linked with hyperphagia and obesity." (PMID 34394087, 2021). "It has been stated that brain area-specific BDNF levels might be associated differentially to energy intake and expenditure when investigating normal-weight participants and patients suffering from obesity." (PMID 33367955, 2021). "Thus, in inflammatory conditions such as obesity and type 2 diabetes, immune cells (via increased IL-6) are stimulated to produce neurotrophins, like BDNF, to minimize the neuronal damage associated with obesity." (PMID 34957187, 2021). "The present study, therefore, examined whether 5-HT and BDNF mediates the association between overweight/obesity and EC." (PMID 33916706, 2021). "Accordingly, mutations in the BDNF gene lead to insatiable appetite and severe obesity." (PMID 34063496, 2021). "To further elucidate the biological and neural underpinnings of obesity, we investigated the association between BDNF levels and brain response to food stimuli and craving in patients suffering from obesity and normal-weight participants by conducting a prospective case–control fMRI study." (PMID 33367955, 2021). "Intriguingly, visual food cues elicited higher insula activation in patients suffering from obesity and higher BDNF levels in patients suffering from obesity were associated with higher cue-reactivity in the bilateral insulae if compared to non-obese participants." (PMID 33367955, 2021). "We are the first to test the hypothesis that BDNF levels might be associated with neural reactivity to food cues in patients suffering from obesity and healthy controls." (PMID 33367955, 2021). "Furthermore, mutations in the gene encoding BDNF are associated with eating disorders inducing obesity, hyperactivity as well as impaired cognitive functions." (PMID 34833132, 2021). "Moreover, microglia release BDNF to support the surrounding neurons that regulate appetite; mice with BDNF deficiency in microglia show hyperphagia and obesity." (PMID 34720877, 2021). "Both the LEPR gene variant (rs1137101) and the BDNF gene variant (rs925946) showed strong association with obesity in the association analysis, as indicated by the beta values (1.068 (0.360; 1.777I), p = 0.003; and 1.237 (0.414; 2.059), p = 0.003, respectively)." (PMID 34685457, 2021). "Additionally, the effect of a multidisciplinary obesity weight loss treatment program on BDNF levels in this population is also investigated." (PMID 35127775, 2021). "Moreover, microglia release neurotrophic factors to support the surrounding neurons that regulate appetite; mice with BDNF deficiency in microglia show hyperphagia and obesity." (PMID 34720877, 2021). "In line with this, selective deletion of the BDNF gene in the ventromedial hypothalamus caused moderate hyperphagic obesity, while deletion of the BDNF gene in CaMKIIα-expressing neurons in mice resulted in severe obesity." (PMID 33367955, 2021). "Based on the hypothesis that BDNF acts as an anorexigenic agent, it seems counterintuitive that higher BDNF levels were associated with higher visual food cue-reactivity in patients suffering from obesity." (PMID 33367955, 2021). "Drawing on literature showing that overweight/obesity is associated with EC, and 5-HT and BDNF are related to overweight/obesity and EC, we hypothesized that 5-HT and BDNF would mediate the association between overweight/obesity and EC." (PMID 33916706, 2021). "Our findings that rs925946 showed a strong association with obesity, however, supports the theory that BDNF may indeed be involved in linking obesity with psoriasis in the early-onset group of patients." (PMID 34685457, 2021).